GCLC (glutamate-cysteine ligase catalytic subunit)
Diseases named in the same sentence as GCLC in open-access papers (continued):
Sharing a sentence is not in itself a finding about the gene and the disease.
periodontitis (1 paper, 2024). An acute or chronic inflammatory process that affects the tissues that surround and support the teeth. "Moreover, we found specific proteins - drivers or suppressors - associated with ferroptosis (SNCA, FTH1, HSPB1, CD44, and GCLC), revealing the co-occurrence of this specific type of regulated cell death during the clinical progression of periodontitis." (PMID 38802345, 2024).
pheochromocytoma (1 paper, 2021). "The reduced GCLC expression increased the methylglyoxal-induced pheochromocytoma cells apoptosis." (PMID 34671271, 2021).
prostate carcinoma (1 paper, 2025). A carcinoma that arises from epithelial cells of the prostate gland. "The observation that MMTSO caused downregulation of GCLC, GSR, and NQO1 genes provides evidence that MMTSO could play a role in oxidative stress and antioxidant defense of prostate cancer." (PMID 40059483, 2025).
psychosis (1 paper, 2022). "Interestingly, in early psychosis patients, low prefrontal GSH levels were associated with high-risk GCLC genotypes, highlighting GCLC polymorphisms should be considered in pathology studies of cerebral GSH." (PMID 34759358, 2022).
rectal cancer (1 paper, 2025). A primary or metastatic malignant neoplasm that affects the rectum. "In vitro combination drug screens identified RRx-001 and inhibition of GCLC as a highly effective and synergistic combination treatment in killing radioresistant rectal cancer organoids." (PMID 40204947, 2025). "Combining RRx-001 with the inhibition of GCLC may be a promising alternative treatment strategy in radioresistant rectal cancer." (PMID 40204947, 2025).
Renal cyst (1 paper, 2024). A fluid filled sac in the kidney. "Levels of GSH biosynthetic enzymes were also downregulated in renal cysts, including the catalytic subunit of the rate-limiting enzyme glutamyl cysteine ligase (GCLC, −2.5×), glutathione synthetase (GSS, −1.9×), and glutathione reductase (GSR, −2.3×)." (PMID 39000280, 2024).
Stroke (1 paper, 2022). Sudden impairment of blood flow to a part of the brain due to occlusion or rupture of an artery to the brain. "In addition, SNP rs648595 of the GCLC gene was associated with increased stroke risk, but at a borderline statistical level." (PMID 35455093, 2022).
urinary bladder cancer (1 paper, 2025). A primary or metastatic malignant neoplasm involving the bladder. "A urinary bladder cancer study found GCLC, GCLM, HMOX1, and NQO1 to be upregulated." (PMID 41109135, 2025).
Waldenstrom macroglobulinemia (1 paper, 2024). "Increased expression of glutamate-cysteine ligase catalytic subunit (GCLC) and solute carrier family 7 member 11 (SLC7A11) can regulate GSH metabolism, promote GSH synthesis, and markedly increase the proliferation of Waldenstrom macroglobulinemia cells." (PMID 39091635, 2024).
cancer (63 papers, 2012 to 2025). A tumor composed of atypical neoplastic, often pleomorphic cells that invade other tissues. "Various studies have found out that high expressed GCLC was associated with the poor prognosis and drug resistance of a variety of cancers." (PMID 39150660, 2025). "Increased GCLC levels have been observed in several cancers, and high GCLC expression has been associated with drug resistance." (PMID 37917375, 2024). "LINC00942 is rarely studied in cancer, and it is believed to promote the expression of GCLC, thereby causing poor prognosis for patients." (PMID 33585468, 2020). "ARID1A mutations increase the sensitivity of these cancer cells to GCLC depletion, indicating that targeting GCLC could selectively attack cancer cells while sparing normal cells, thereby reducing the risk of excessive ROS buildup and DNA damage." (PMID 41333220, 2025). "Pre‐clinical and clinical studies suggest that this upregulation might render HIV‐infected and cancer cells more susceptible to pharmacologically induced oxidative bursts, namely through the inhibition of the Nrf2 targets TrxR1 and GCLC." (PMID 32157726, 2020). "Also, it has recently been shown that ARID1A mutations can render cancer cells sensitive to glutathione and glutamate-cysteine ligase synthetase catalytic subunit (GCLC) inhibitors, while they also increase the sensitivity of cancer cells to PI3K inhibitors." (PMID 32520976, 2020). "Specifically, the effect of NSUN2 lactylation-GCLC-GSH pathway is nearly lost when NSUN2 K508R or GCLC C-A mutant (five cytosine sites) was introduced into the cancer cells." (PMID 39742570, 2025). "Overall, our present study demonstrated that NAA10-catalyzed lactylation of NSUN2 potently promotes cancer cell survival through a GCLC-dependent glutathione synthesis." (PMID 39742570, 2025). "Overall, these findings imply that GCLC is an indispensable downstream effector of lactylated NSUN2 in modulating ferroptosis resistance to promote cancer cell survival." (PMID 39742570, 2025). "Our study provides the compelling evidence that lactate can serve as a signaling molecule to lactylate and activate NSUN2 catalyzing m5C formation and maintaining mRNA stability of GCLC, by which cancer cells can avoid ferroptotic cell death under acidic TME." (PMID 39742570, 2025). "NRF2-induced antioxidant genes, such as NQO1, HO-1, and GCLC, help mitigate oxidative stress, which is often elevated in cancer-prone tissues." (PMID 41333220, 2025). "Here, we demonstrated that GCLC, the enzyme involved in GSH synthesis, is essential for BL cell lines and showed the potential of the GCLC inhibitor BSO as an anti-cancer agent." (PMID 37917375, 2024). "Our data validate previous studies of GCLC expression in hyperglycemic patients, beyond the cancer context." (PMID 37380658, 2023). "Numerous studies have indicated that the transcription of GCLC is controlled by nuclear factor erythroid 2-related factor 2 signaling, and that it correlates with prognosis in various cancers." (PMID 38049865, 2023). "The SLC7A11 and GCLC are core regulators of ferroptosis and have been studied as promising targets in cancer." (PMID 37237981, 2023). "The nuclear translocation of the Nrf2 activates the ARE-gene cluster (including GCLC, Nqo1, and HO-1) facilitating ROS-mediated apoptosis in neuroinflammation ultimately leading to neurodegeneration and cell death in cancer cells." (PMID 35360165, 2022). "An increase in the levels of GCLC transcript and protein often leads to a decrease in cancer cell proliferation and lower intracellular ROS." (PMID 35360165, 2022). "The corresponding heatmap data among pan-cancer show a positive correlation between ABCG2 and EPAS1, and GCLC in most cancer types." (PMID 36555598, 2022). "GCL is a heterodimeric holoenzyme that is composed of catalytic (GCLC) and modifier (GCLM) subunits; the expression levels of GCLC and GCLM are highly associated with the drug sensitivity of cancer cells and patient survival." (PMID 35740025, 2022).
cancer (continued). "The regulation of GCLC expression by Myc also occurs in effector T cells and this can regulate immunotherapeutic responses in cancer patients." (PMID 33381452, 2020). "As GCLC-catalyzed GSH synthesis plays a key role in redox homeostasis and ferroptosis sensitivity, we further evaluated whether NSUN2 lactylation regulates GCLC-dependent sensitivity to ferroptosis in cancer cells." (PMID 39742570, 2025). "Furthermore, GCLC plays a crucial role in drug resistance and is considered to be a potential drug target in lung and other cancers." (PMID 29050246, 2017). "Thus, SLC7A11 and GCLC expression could be defined as a cancer signature of GAS41 amplification in NSCLC (KEAP1 and NFE2L2 WT)." (PMID 38514704, 2024). "While some cancers exhibit reduced GCL activity and low glutathione levels, gynecological cancers such as endometrial and ovarian subtypes often display elevated GCLC expression, conferring metabolic flexibility and resistance to therapy." (PMID 41333220, 2025). "Our study demonstrates that GCLC mRNA, the catalyzing enzyme subunit of GSH synthesis, is the special target of lactylated NSUN2, through which cancer cells maintain a redox homeostasis under acidic TME." (PMID 39742570, 2025). "The NSUN2 lactylation promotes its enzymatic activity to catalyze m5C modification on target GCLC mRNA, leading to upregulated GCLC expression and GSH synthesis rendering cancer cells resistant to ferroptosis." (PMID 39742570, 2025). "Specifically, targeting key antioxidant proteins, such as SLC7A11, GCLC, GPX4, TXN, and TXNRD, represents an emerging approach for inducing oxidative cell death in cancer cells." (PMID 39090114, 2024). "Our results showed significant downregulation in expression of essential genes related to ferroptosis, namely SLC7A11, GCLC, MAP1LC3A, and SLC39A8 in NAT10-depleted cancer cells." (PMID 37237981, 2023). "Expression levels of the ferroptosis-related genes GCLC, MAP1LC3A, SLC7A11, and SLC39A8 in NAT10 KD cancer cells were significantly downregulated, therefore validating the results from our RNA-seq data." (PMID 37237981, 2023). "We assessed 19,221 genes and observed a positive correlation between FIN sensitivity and the expression of several well-known NRF2 targets, including NQO1, SLC7A11, GPX2, GCLC, and FTH1, across various cancer cell lines at both the mRNA and protein levels." (PMID 37633973, 2023). "BSO, a GCLC inhibitor, is used as a drug to deplete GSH, but this drug results in GSH reduction, not only in cancers, but also in normal tissues." (PMID 35106124, 2022). "Consistent with our prior observations, and those of others, that eprenetapopt triggers GSH depletion in cancer cells, the CRISPRko screen identified genes involved in GSH synthesis, SLC7A11 and GCLM, while GCLC was the top enriched gene in the CRISPRa screen." (PMID 36103522, 2022). "We further verified the expressions of the oxidative stress-responsive genes and the cholesterol biosynthesis-related genes using qPCR in the GBM cancer cells and recorded an increase in the mRNA levels of HMGCR, HMCGS1, DHCR24, GSR, GSTM2 and GCLC after MPT0L145 treatment in U87MG and M059K cells." (PMID 34885226, 2021). "Although the molecules and pathways involved in GSH synthesis, such as xCT and GSH/GCLC, are closely related to ferroptosis, they reported here that the inhibition of GSH/GCLC in ARID1A-deficient cancer cells caused apoptosis by ROS, but not ferroptosis." (PMID 34502181, 2021). "Similarly, we observed that the expression of GCLC, NLRP3 and CD47 are downregulated in both groups of non-cancer cells treated with either LIUS or mild hyperthermia." (PMID 31355136, 2019). "Furthermore, NRF2 target genes were overexpressed in various cancer cells after PDT, which include HO-1, GCLC and GCLM subunits of GCL, NQO1, and ABCG2." (PMID 26516076, 2015).
cancer (continued). "It has been shown that curcumin activated NRF2 in several cell types and exerted a cytoprotective effect through transcriptional induction of phase II enzymes, such as glutathione transferase, NQO1, HMOX-1, GCLC, and GCLM in certain human cancers, skin lesions, and neurodegenerative diseases." (PMID 23710286, 2013). "GCLC and glutathione synthetase (GSS), whose genes were identified by our analysis to be highly overexpressed in cancers and to confer bad prognosis in patients, are both essential enzymes catalyzing the synthesis of glutathione from glutamate, cysteine and glycine." (PMID 24342878, 2013). "Thus, high basal GCLC and HMOX1 may support the tumorigenic behavior of cancer cells chronically exposed to IL-1." (PMID 39936983, 2025). "Results showed that the expression of GCLC, SOD1 and SLC7A11 in ML385 treatment groups significantly decreased compared to that of the control groups, and the reduced antioxidant capacity re-increased the oxidative stress levels, resulting in the slowing-down of cancer cell proliferation." (PMID 37682862, 2023). "In an in vitro study, the expression of the genes glutamate cysteine ligase (GCLC) and glutathione synthetase (GSS) that synthesize GSH and GSH-Px gene were verified by qPCR and subjected to treatment with doxorubicin, to check the resistance of cancer cells to chemotherapy." (PMID 24565113, 2014).
tumor (59 papers, 2012 to 2026). "GCLC plays crucial roles in various tumor-associated biological processes, such as tumor proliferation, resistance to ferroptosis, chemoresistance, and immune evasion." (PMID 40113760, 2025). "The increases in Nrf2 and GCLC following RT were similar in normal and tumor-associated adipose tissue." (PMID 31752313, 2019). "GCLC loss in Tregs can elevate serine metabolism and ROS levels that impair the suppressive activity of Tregs, which further aggravates inflammation but hampers tumour growth." (PMID 40045458, 2025). "Thus, ARID1A-loss tumor cells must rely on the glutamate-cysteine ligase synthetase catalytic subunit (GCLC), a rate-limiting enzyme for GSH synthesis, to produce cysteine necessary for GSH production." (PMID 38347608, 2024). "Intriguingly, two cell lines including SNU-16 and MKN45, present much higher GCLC protein levels in relative to other four tumor cell lines, and both the intracellular lactate and total GSH levels were also higher." (PMID 39742570, 2025). "Conversely, the downregulation of NFS1, GCLC, TP63, CD44, and SRC suggests a potential attenuation of antioxidant defense systems, thereby predisposing tumor cells to lipid peroxidation-mediated cell death." (PMID 40868287, 2025). "Treatment with BARD increased GCLC protein levels and NF-κB p50 activation in the kidneys, while cisplatin treatment increased tumor Nrf2 activation and NF-κB p65 activation in the kidneys." (PMID 40881130, 2025). "Clinical trials have confirmed the safety of the GCLC inhibitor BSO in combination with chemotherapy for other tumor types." (PMID 40113760, 2025). "Several studies have demonstrated that the expression of GCLC is significantly elevated in tumor tissues and positively correlates with prognosis in patients with malignancies." (PMID 40113760, 2025). "In another study, the histone methyltransferase G9a has been found to activate GCLC expression and enhance tumor drug resistance." (PMID 40113760, 2025). "There was good concordance between SLC7A11 (which encodes xCT), NQO1, GCLC and GCLM median expression levels across tumours, providing an ‘antioxidant signature’ associated with the NRF2 transcriptional programme." (PMID 39690148, 2024). "There was good concordance between SLC7A11 (which encodes xCT), NQO1, GCLC and GCLM median expression levels across tumours, providing an ‘antioxidant signature’ associated with the NRF2 transcriptional program." (PMID 38168428, 2023). "The GCLC expression significantly decreased in tumor tissue compared with normal liver tissue from HCC patients with MC exposure." (PMID 36851037, 2023). "When it comes to in vivo conditions, tumor xenografts of GCLc-KO cells surprisingly grew somewhat faster in comparison with their WT counterpart." (PMID 35804926, 2022). "Treatment of LT2-MYC tumor-bearing mice with a locked-nucleic acid antagonist of miR-18a significantly rescued GCLC expression and glutathione levels in vivo." (PMID 28443280, 2017). "With a decrease, tumors were found to be sensitive to an inducer of oxidative stress, while an increase led the tumors to be sensitive to GCLC inhibition during the early phase of tumor formation." (PMID 28443280, 2017). "And functionalized macromolecules, such as green fluorescent protein (GFP), tumor-specific apoptosis inducer Apoptin as well as biological active enzyme GCLC (Glutamate-cysteine ligase, catalytic subunit) can be delivered by hPP10 in vitro and in vivo." (PMID 27081693, 2016). "Therefore, we reasoned that blocking the Glu‐GSH flux using a GCLC inhibitor would increase the antigen presentation in tumor cells and enhance the efficacy of ICB therapy in treating CRC." (PMID 39482885, 2025). "Additionally, we evaluated variances in immune cell infiltration, tumor mutation burden, and TIDE scores between the high- and low-risk groups, along with the expression levels of GCLC and HSBP1." (PMID 39150660, 2025).
tumor (continued). "Additionally, in vivo, tumorigenicity of NC and GCLC knockdown CCSCs was examined using limiting dilution assays (LDAs), monitoring tumor latency, incidence, and growth rate." (PMID 40113760, 2025). "To validate it, we sought to determine whether inhibiting GCLC (M27) or GLUD1 (M28) increases MHC‐I antigen presentation in tumor cells." (PMID 39482885, 2025). "This is a favorable result as increased GCLC protein in the tumor could result in decreased anti-tumor efficacy from cisplatin treatment." (PMID 40881130, 2025). "GCLC knockdown exhibited reduced tumor-initiating capacity and formed smaller tumors." (PMID 40113760, 2025). "Relatively low expression of GCLC in EGFR-overexpressing GBM may keep ROS at a threshold favorable for ROS tumor-promoting functions." (PMID 39001381, 2024). "As a result, inhibition of GCLC activity could be a potential therapeutic strategy by exposing more tumor cells to ROS attack." (PMID 38347608, 2024). "Molecular analyses of tumors exposed to high glucose levels reveal that the expression of GCLC (glutamate-cysteine ligase catalytic subunit), a key component of glutathione biosynthesis, is diminished, which in turn augments oxidative anti-tumor damage by chemotherapy." (PMID 37380658, 2023). "Furthermore, in the subsequent experiments, we will construct shRNA to stably knock down GCLC and then observe its effect on the tumor for the reason that the si-RNA we used in this experiment can only briefly knock down GCLC." (PMID 36359768, 2022). "Based on our previous experience with xCT-KO cell growth in vivo, a potential explanation for GCLc-KO tumor cell survival and proliferation in the same conditions could be attributed to GSH exchange between GCLc-KO and the neighboring WT cells in the tumor mass." (PMID 35804926, 2022). "Therefore, we infer that in the development of LUAD, the upregulation of GCLC expression may lead to the increase in type 2 T helper cell content, thereby promoting tumor immune escape." (PMID 36359768, 2022). "Furthermore, histological examinations showed that levels of YAP, GSR, and GCLC proteins were concomitantly elevated in Py8119 tumor tissues from obese mice, compared to those in lean mice, but increased expressions of YAP, GSR, and GCLC were reduced by YAP‐knockdown." (PMID 35182054, 2022). "Indeed, the authors found that BSO, an inhibitor of GCLC, could reduce sympathetic ganglia hyperplasia and delay tumor onset when given prophylactically." (PMID 28443280, 2017). "Elevated GCLC and HMOX1 correlate with poor prognosis, tumor progression, and treatment resistance, including CRPC." (PMID 39936983, 2025). "Pharmacological inhibition of GCLC, a key enzyme in the Glu‐GSH flux, also elevated tumor antigen presentation and sensitized colorectal tumors to anti‐PD‐1 therapy." (PMID 39482885, 2025). "Knockdown of SLC7A11 in tumor cells, overexpression of SLC7A11 in T cells, overexpression of GCLC in T cells, and cystine supplementation enhanced the anti-tumor ability of CD8+ T cells." (PMID 40018041, 2025). "Meanwhile, protein levels of GAS41 declined in line with significantly decreased protein levels of SLC7A11 and GCLC, suggesting that GAS41-mediated antioxidant regulators expression is critical for tumor growth in vivo." (PMID 38514704, 2024). "WT and GCLc-KO cells of Capan-2 cell lines treated with 3 mM GSH were injected subcutaneously with matrigel into nude mice and tumor growth was monitored." (PMID 35804926, 2022). "This pattern of enrichment in AC and SCC was also seen with the other NRF2 target genes, GCLC, GCLM and NQO1, although HMOX1 was downregulated in both tumour types." (PMID 27824809, 2016). "Several studies have shown coordinated overexpression of GCLC and MRP in drug-resistant tumor cell lines, in human colorectal tumors and in human lung cancer specimens after platinum exposure." (PMID 23766865, 2013).